PRDM16-DT (PRDM16 divergent transcript)
Synonyms: FLJ42875; lnc-dPrdm16; LINC00982
Gene: Long non-coding RNA gene on chromosome 1 (3,059,564 to 3,070,251, reverse strand). Ensembl gene ENSG00000177133.
Diseases named in the same sentence as PRDM16-DT in open-access papers:
PRDM16-DT is named in the same sentence as 7 diseases in open-access papers, as found by Europe PMC text mining. Sharing a sentence is not in itself a finding about the gene and the disease.
PRDM16-DT shares sentences with these, for which no sentence is quoted: gastric cancer (3 papers); cancer (2); tumor (2); breast carcinoma (1); colorectal cancer (1); lung adenocarcinoma (1); renal carcinoma (1).